HIF1A (hypoxia inducible factor 1 subunit alpha)
Diseases named in the same sentence as HIF1A in open-access papers (continued):
Sharing a sentence is not in itself a finding about the gene and the disease.
cancer (continued). "HIF-1α signaling is critical for the regulation of multiple tumorigenic properties such as cancer cell survival under hypoxic stress, invasion, and chemoresistance." (PMID 38547055, 2024). "Coordinate expression of HIF-1α and β-catenin has been shown to play a profound role in TNBC tumorigenesis and their transcriptional activity is associated with cancer relapse and poor survival." (PMID 38962320, 2024). "All these data point to a glycolytic activity, which is considered one of the cancer hallmarks under the influence of HIF-1A." (PMID 39567394, 2024). "HIF-1 is the key master regulator of hypoxia status and hypoxia-inducible factor 1-alpha (HIF-1α) has been shown to be overexpressed in many cancer types and is associated with cancer progression." (PMID 38535967, 2024). "Hypoxia-inducible factor 1α (HIF-1α), an oxygen-dependent transcription factor, is critical for the adaptive response to hypoxic environments and contributes to cancer cell survival and progression." (PMID 39682267, 2024). "Molecular analyses have confirmed that the density of hypoxia-Inducible factor-1 alpha (HIF-1α) is high in hypoxic cancer cell Exos." (PMID 38360641, 2024). "Infection with oncolytic NDV AF2240 degrades HIF-1α under hypoxia, down-regulating HIF-1α target genes in cancer cells." (PMID 39684701, 2024). "HIF-1α plays a critical role in cancer survival and proliferation in hypoxic environments by regulating a wide range of genes." (PMID 38424190, 2024). "Here, the authors examine cancer resistance mechanisms across seven bat species using in vitro and in vivo models, and identify HIF1A, COPS5, and RPS3 as related genes." (PMID 38360878, 2024). "When cancer cells detect a hypoxic environment, hypoxia-inducible factor 1 alpha (HIF1α) is stabilized." (PMID 38344066, 2024). "In this study, HIF-1α expression was upregulated in most TCGA cancers specifical the solid cancer types." (PMID 38678297, 2024). "Although HIF-1α represents a major player and a potential target of hypoxia in cancer, its inhibition raises some concerns of unintentional side effects linked to its ubiquitous expression pattern especially in non-tumoral sites." (PMID 39003252, 2024). "The HIF-1α protein is an imperative regulator of this process and is involved in cancer development." (PMID 38662225, 2024). "By elucidating the complex interplay between HIF-1α and cancer, this review seeks to highlight potential avenues for novel and more effective cancer therapies, ultimately contributing to improved patient outcomes." (PMID 39493156, 2024). "The binding of ISG15 with hypoxia-inducible factor 1-alpha (HIF-1α) impairs HIF-1α-targeted gene expression and cancer cell proliferation." (PMID 38675828, 2024). "Long term survival of cancer cells in hypoxia is dependent upon HIF1α activity for energy production." (PMID 38485816, 2024). "Taken together, the Yin group here has identified a hypoxia-triggered HIF-1α/miR-338-5p/IL-6 feedback loop, offering a direction for future research in cancer therapy." (PMID 37588219, 2024). "Under hypoxic conditions, HIF-1α can regulate the polyamine biosynthetic and homeostatic pathways in cancer cells and other cellular systems such as retinal glial cells." (PMID 38547055, 2024). "Inhibiting HIF-1α activity can limit cancer progression, and HIF-1α is considered a feasible target for cancer treatment." (PMID 39766299, 2024). "Alcohol-induced NFATc2 expression upregulated the expression of genes involved in glycolysis and cancer stemness (HIF1α, TP1, ENO1, PKM2, ALDH1A, Bmi1, and Oct4) in OSCC." (PMID 39169426, 2024). "Activated p-Akt can further activate mTOR and regulate HIF-1α, playing a central role in glycolysis, cancer metabolism, and cancer cell proliferation." (PMID 39741958, 2024).
cancer (continued). "By specifically targeting HIF-1α, siRNAs offer a precise method for managing cancer and improving treatment outcomes." (PMID 39493156, 2024). "In OSCC, HIF1A contributes to the invasive and metastatic potential of cancer cells by modulating pathways that enhance cell motility and invasion." (PMID 39458948, 2024). "Accordingly, inhibition of HIF-1α or reduction of hypoxia has been reported to unleash T cell activity and sensitize cancer to ICI." (PMID 38175205, 2024). "M4N is a dual inhibitor of SP1 and HIF1A but only occasionally works as a MYC inhibitor for certain cancer cells specifically." (PMID 39590335, 2024). "Subsequently, HIF-1α is involved in angiogenesis, glucose metabolism, cancer cell invasion and metastasis, and immune escape by regulating the expression of target genes." (PMID 38799423, 2024). "Recently, therapeutic strategies targeting both HIF-1α and NF-κB have been explored in cancer treatment, showing promise not only in improving treatment efficacy but also in reducing side effects." (PMID 39766299, 2024). "ST3G5 expression in cancer cells regulates hypoxia‐inducible factor 1‐alpha (HIF1α) and downstream target molecules." (PMID 37716915, 2024). "In summary, by inhibiting HIF-1α, reducing angiogenesis, and increasing oxidative stress within cancer cells, both hyperbaric oxygen and ozone therapy can complement traditional cancer treatments and improve patient outcomes." (PMID 39376991, 2024). "HIF-1α’s primary function is to enable cells to adapt to low oxygen, making it a critical player in the survival of both normal and cancer cells." (PMID 38257813, 2024). "In patients with ccRCC, the nuclear expressions of HIF-1α and HIF-3α was significantly associated with cancer-specific survival (CSS) in univariate analysis." (PMID 38571885, 2024). "Most ccRCC cases are connected with the inactivation of the cancer inhibitor gene von Hippel–Lindau (VHL), which causes the dysregulation of hypoxia-inducible factors 1 alpha (HIF1α) and 2 alpha (HIF2α) through the ubiquitin-dependent degradation pathway." (PMID 38390305, 2024). "PTEN loss results in increased Akt activity (pAkt) and NF-κB activation, leading to the induction of HIF-1α expression in various cancers." (PMID 39063014, 2024). "Hypoxia-inducible Factor 1α (HIF1α) and HIF2α are broadly expressed in many human cancers, and the expression of these proteins frequently correlates with poor patient prognosis." (PMID 38263248, 2024). "Specifically, many critical enzymes of the glycolytic pathway are targets of HIF-1α, which is thought to mediate the activation of glycolysis in cancer cells." (PMID 37588219, 2024). "siRNA targeting HIF-1α: Specific siRNAs can be designed to target and degrade the mRNA of HIF-1α, effectively reducing its expression and activity in cancer cells." (PMID 39493156, 2024). "Under hypoxic conditions, HIF-1α upregulates PD-L1 on cancer cells and MDSCs, thereby interfering with T cell effector function." (PMID 38778409, 2024). "While HIF-1α, often found upregulated in cancer, has the capacity to regulate the expression of Axl, Axl also seems to be important in the transcription and stability of HIF-1α." (PMID 38298195, 2024). "HIF-1α binds to various enzymes and leads to modification of metabolic pathways such as angiogenesis in cancer cells, this encourages the growth of tumors tissue." (PMID 39049021, 2024). "HPV 16 E6 and E7 oncoproteins increase metabolic reprogramming, one of the hallmarks of cancer, by increasing the stability of hypoxia-induced factor 1 α (HIF-1α) and consequently increasing the expression levels of their target genes." (PMID 38921041, 2024). "HIF-1α-induced upregulation of PDK1 inhibits PDC activity, causing a shift in the cancer cell metabolism towards anaerobic glycolysis, and decreases the production of ROS." (PMID 38255882, 2024). "Such synergy offers an effective strategy to impair cancer cell growth by targeting HIF1α stability through complementary mechanisms." (PMID 39697237, 2024).
cancer (continued). "The produced lactate stabilizes HIF-1α and creates an acidic condition in cancer cells environment, and promotes cancer invasion and metastasis." (PMID 38674143, 2024). "The malignant feedback loop formed by the proteins EZH2 and HIF-1α often leads to unfavorable prognoses in a variety of cancers." (PMID 38911968, 2024). "HIF1A, hypoxia-inducing factor, promotes angiogenesis and is important for the vascular system in the embryo and for cancer tumors." (PMID 39691708, 2024). "It has been reported that HIF-1a/PI3K signaling pathway plays a promoting role in other malignant tumors." (PMID 39050762, 2024). "SMURF2 targets HIF1α for ubiquitination and subsequent proteasomal degradation, disrupting hypoxic responses that promote cancer cell survival, metabolic reprogramming, angiogenesis, and resistance to therapy." (PMID 39697237, 2024). "MALAT1 stabilized δ‐catenin protein and upregulated HIF‐1α gene expression, both of which are master regulators of cancer glycolysis." (PMID 38639382, 2024). "Other research showed that honokiol (HNK) downregulates levels of HIF-1α and its associated factors (such as PDK1, HK2, and GLUT1), inhibiting HIF-1α-dependent glycolysis and inducing cancer cell death through apoptosis." (PMID 39421736, 2024). "Lactate is also known to activate the mTORC1 complex in cancer cells, and the activation of mTOR signals via HIF1α, initiates VEGF expression in FCDIIb." (PMID 39483922, 2024). "The different levels of HIF-1A expression have been used to represent hypoxia in cancer cells and demonstrate hypoxia-mediated alterations in the expression of genes involved in the glycolysis pathway, specifically in lactate accumulation." (PMID 39567394, 2024). "It inhibits NADPH oxidase 4 (NOX4) and HIF1α, two key players in cancer cell survival, which in turn suppresses PKM2 and disrupts the Wnt/β-catenin signaling pathway-a critical process in cell proliferation." (PMID 39479443, 2024). "This is critical as targeting HIF1α signaling pathways is a focus of ongoing research to develop novel cancer treatments." (PMID 39697237, 2024). "The overexpression of HIF-1α and VEGF has been associated with poor prognosis in various cancer types." (PMID 39597826, 2024). "HIF-1α is a classical transcription factor that regulates glycolytic activity to sustain cancer survival and progression." (PMID 39816354, 2024). "HIF1α and HIF2α are broadly expressed in many human cancers and are the most important downstream biomolecules of VHL." (PMID 38263248, 2024). "Cancer cells activate HIF-1α in response to hypoxia, which sets off a transcriptional cycle that facilitates survival and adaption to low oxygen situations." (PMID 39493156, 2024). "In HNSCC, SLUG is responsible for the switch from E-cadherin to N-cadherin under hypoxic conditions and after hypoxia-inducible factor 1-alpha (HIF-1α) overexpression in cancer cell lines." (PMID 38611032, 2024). "HIF-1α is maintained at low intracellular levels in EBV+ cancer cells due to the overexpressed neddylation pathway, which leads to the failure of lytic induction therapy." (PMID 39062453, 2024). "On the other hand, hypoxia can also directly increase the expression of PD-L1 in myeloid-derived suppressor cells, dendritic cells, and cancer cells by activating HIF-1α." (PMID 38365678, 2024). "The flavonoid significantly increased the sensitivity of resistant cells to tamoxifen by inhibiting cell proliferation and inducing apoptosis via the inhibition of HIF-1α, a protein that promotes cancer growth." (PMID 38893380, 2024). "On the other hand, higher expression of HIF1α has been shown in various cancers to indicate drug resistance." (PMID 38874588, 2024). "KEGG enrichment analysis indicated that these hub genes were partially involved in ECM-receptor interactions, the HIF-1α signaling pathway, and some cancer-related pathways." (PMID 38443979, 2024).
cancer (continued). "For instance, metformin not only downregulates the expression of PDK1 to overcome cisplatin resistance but also reduces the levels of HIF-1α in drug-resistant cancer cells and interferes with the transcription of glucose metabolism-related genes." (PMID 38577616, 2024). "Anesthetics can influence immune-modulating cytokines, induce pro-inflammatory factors such as HIF-1α, and alter natural-killer cell activity, affecting cancer cell survival and spread." (PMID 39597826, 2024). "This hypoxic environment activates the production of hypoxia-inducible factor 1-α (HIF1α), which not only suppresses anti-cancer immune responses but also promotes cancer invasion and metastasis." (PMID 39346906, 2024). "HIF-1 itself is a heterodimer of α and β subunits, with HIF-1α particularly induced under hypoxia to regulate genes related to cancer cell proliferation and angiogenesis." (PMID 39737184, 2024). "Databases and human cancer tissue samples were analyzed to investigate the roles of PDLIM2 and HIF-1α in cancer growth." (PMID 38880883, 2024). "It has been suggested that a high amount of lactate (10mM) in cancer stimulates HIF-1α and angiogenic precursors such as VEGF." (PMID 38542288, 2024). "The specific pathways were the cancer pathway, MAPK signaling pathway, Foxo signaling pathway, microRNAs in cancers, and HIF1A signaling pathway." (PMID 39258670, 2024). "USP43, USP52, JOSD1, UCHL5 and OTUB1 all reduced levels of the HIF-1α target CA9 in the secondary validation screen in two different non-cancer cell lines." (PMID 39009674, 2024). "Malignant tumors contain various strategies to adapt to hypoxic conditions, with significant research focusing on hypoxic markers, such as HIF-1α and GLUT-1." (PMID 39202223, 2024). "CRLX101, a nanoparticle-drug conjugate, delivers camptothecin to cancer cells, sustaining HIF-1α inhibition and showing synergistic effects with anti-angiogenesis drugs like bevacizumab in rectal cancer models." (PMID 39683818, 2024). "Transcriptional Regulation: Activated AKT can also enhance the transcription of HIF1α by promoting its translation and increasing its mRNA levels, further contributing to its accumulation and activity in cancer cells." (PMID 39272694, 2024). "HIF-1α also increases the expression of genes that drive increased glycolysis in cancer cells, thus providing a potential mechanism to coordinate glycolysis and PCK as noted in our results." (PMID 39479019, 2024). "The crucial role of HIF1α in cancer progression has catalyzed the development of numerous inhibitors targeting its various functions, which are currently under investigation in pre-clinical and clinical stages." (PMID 39697237, 2024). "HIF-1α is an important player in cancer progression because it promotes angiogenesis, metabolic reprogramming, and cell survival in low-oxygen environments." (PMID 39493156, 2024). "The intricate cross-talk between HIF-1α, TGF-β, and other signaling pathways underscores the complexity of cancer progression and challenges associated with targeted interventions." (PMID 38542288, 2024). "In CLL cells, HIF-1α can regulate the expression of chemokine receptors and cell adhesion molecules, which in turn govern the interaction of cancer cells with the BM and spleen microenvironment." (PMID 37588219, 2024). "Elevated ROS from mitochondrial dysfunction can promote cancer cell proliferation by activating HIF1α and stimulating calcium signaling through STIM1 and SOCE." (PMID 39104527, 2024). "Research has shown that HIF-1α is significantly present in many cancerous cells and plays a key role in inflammation, the development of tumors, and the ability of cancer cells to resist drugs when oxygen levels are low." (PMID 39518022, 2024). "HIF1α signaling also promotes lipid uptake by increasing the expression of lipoprotein receptors in cancer cells." (PMID 39284708, 2024).
cancer (continued). "We chose HIF1a as our antisense target as it is a prevalenttarget for cancer therapies that is upregulated alongside the hypoxicconditions often associated with tumors." (PMID 38346399, 2024). "Conclusively, HIF-1α activation by S1P was observed in various cells, thus, confirming the hindering effect of S1P in anti-cancer imunity." (PMID 38698424, 2024). "This metabolic reprogramming is crucial for the rapid proliferation and survival of cancer cells, making HIF1α a central player in cancer metabolism." (PMID 39107723, 2024). "Research has consistently demonstrated that Hypoxia-inducible factor 1-alpha (HIF-1α) is overexpressed in numerous types of cancer, significantly influencing cancer progression." (PMID 38799423, 2024). "So far, HIF-1α nuclear accumulation in cancer cells triggered by neddylation inhibition has been verified sufficiently." (PMID 39062453, 2024). "Several studies suggested that ROS interact with the HIF1 pathway and alter HIF1α expression in cancer cells." (PMID 39518022, 2024). "It is evident from the figure that CHOL has the largest increase in the expression of HIF1A in cancer vs. control samples across all stages, thereby indicating that CHOL is the most hypoxic cancer type among the seven." (PMID 40708677, 2024). "HIGD1A has a dual effect of promoting and inhibiting cancer and is regarded as HIF-1α’s target genes." (PMID 39108265, 2024). "Cancer cells must adapt to hypoxia to survive, which requires hypoxia-inducible factor 1 alpha (HIF-1α)." (PMID 38766303, 2024). "In conclusion, the data presented in this study strongly suggested a positive correlation between PRMT5 expression and various pro-cancer pathways, notably the HIF1α pathway in HCC." (PMID 38666828, 2024). "There has been an increasing focus in cancer therapeutics on manipulating HIF1α signaling to reconfigure cancer metabolism, which has been a growing interest in cancer therapeutics." (PMID 38339062, 2024). "The expression levels of HIF1α vary significantly among cancers, indicating its utility in patient stratification." (PMID 39697237, 2024). "One of the Fbp2 non-enzymatic functions is the reduction of hypoxia-inducible factor 1α (Hif1α) protein level in cancer cells." (PMID 39251668, 2024). "The resulting hypoxia can induce CAF-like features in normal fibroblasts, and the resulting upregulation of HIF-1α in cancer cells contributes to cancer cell survival following radiotherapy." (PMID 39696386, 2024). "Both mTOR and NF-κB participate in the upregulation of HIF-1α, and three distinct pathways are followed from here to increase the metastasis and migration of cancer cells." (PMID 39014491, 2024). "For instance, in fumarate hydratase-deficient cancer cells, accumulated fumarate results in the production of succinate GSH, resulting in increased mitochondrial ROS and subsequent HIF-1α activation." (PMID 38424190, 2024). "Adaptation to chronic hypoxia occurs through changes in protein expression, which are controlled by hypoxia-inducible factor 1α (HIF1α) and are necessary for cancer cell survival." (PMID 38485816, 2024). "Other mechanisms of HIF1α’s role in chemo- and radio-resistance include activating DNA repair pathways, which allow cancer cells to survive despite treatment-induced DNA damage." (PMID 39697237, 2024). "Cancer cell proliferation can be driven by cellular aspartate, and HIF1α is a direct inhibitor of aspartate biosynthesis." (PMID 39534557, 2024). "The 50:50PLGA-MnO2 NPs exhibited the best short- and long-term controlof hypoxia in cancer spheroids, resulting in sustained regulationof the expression of HIF-1α and immunosuppressive genes." (PMID 38365202, 2024).